CDX2 (caudal type homeobox 2)
Diseases named in the same sentence as CDX2 in open-access papers (continued):
Sharing a sentence is not in itself a finding about the gene and the disease.
mucinous adenocarcinoma (22 papers, 2014 to 2025). An invasive adenocarcinoma composed of malignant glandular cells which contain intracytoplasmic mucin. "CDX2 expression loss was associated with ascending colon (p = 0.03), partially mucinous adenocarcinoma (p = 0.04), poorly differentiated carcinoma (p < 0.001) and dMMR (Fisher’s Exact Test, p < 0.001)." (PMID 37325467, 2023). "dMMR was significantly associated with ascending colon (p < 0.001), mucinous adenocarcinoma (p < 0.001) poorly differentiated carcinoma (p < 0.001), peritumoral lymphocytic infiltration (p = 0.002) and CDX2 expression loss (Fisher’s Exact Test, p < 0.001)." (PMID 37325467, 2023). "CDX2 expression loss was detected in 19 out of 336 CRCs (5.9%) and was associated with ascending colon CRC, partially mucinous adenocarcinoma, poorly differentiated carcinoma, and dMMR." (PMID 37325467, 2023). "The CDX2 expression rates were similar between adenocarcinomas, mucinous carcinomas, and micropapillary carcinomas." (PMID 35328309, 2022). "Most compare their expression with usual ductal adenocarcinomas, and there are none that exclusively analyze more specific markers of intestinal differentiation, such as CDX-2 and beta-catenin in pure mucinous adenocarcinomas of the breast." (PMID 25299496, 2014). "Furthermore, combined use of CDX2 with CK7 can help in this differential diagnosis, as 60% of the primary ovarian mucinous tumors are (CK7+, CDX2−, in contrast to mucinous adenocarcinomas of the lower gastrointestinal tract, where 83% of cases are (CK7−, CDX2+)." (PMID 31771640, 2019). "Postoperative pathology indicated mucinous adenocarcinoma, with immunohistochemistry positive for CK7, CK20, and CDX-2." (PMID 39902031, 2024). "Expression of CDX2 and MDR1 was most pronounced in well‐differentiated mucinous adenocarcinoma and weakest in poorly differentiated ones." (PMID 27060927, 2016). "Postoperative pathological return: prostate adenocarcinoma with mucinous carcinoma differentiation (cancer cells arranged in adenoid pattern and rich in mucus); immunohistochemistry showed: P504s (partially +), CK7 (+), CK20 (partially +), CDX2 (+), B-catenin (plasma, membrane +), PSA." (PMID 40896436, 2025). "The neoplastic cells of metastatic prostatic adenocarcinoma were positive for NKX3.1 and PSA, negative for CDX‐2, CK7, and TTF1; whereas the neoplastic cells of lung mucinous adenocarcinoma were positive for CDX2, CK7, and napsin‐A (focal), negative for TTF1, NKX3.1, and PSA." (PMID 40028792, 2025). "Furthermore, it is important to highlight that primary adenocarcinomas from the upper digestive tract can be positive for both CK7 and CK20 and it should not be forgotten that primary lung mucinous adenocarcinomas are also CDX2-positive." (PMID 36835963, 2023). "Primary ovarian mucinous tumors are invariably diffusely positive for CK7, and negative or focal positive for CK20 and CDX2 while metastatic mucinous carcinomas, particularly those from the lower gastrointestinal tract and appendix, demonstrate the opposite immunoprofile." (PMID 31279332, 2019). "In contrast, immunostains showed that the neoplastic cells of the mucinous adenocarcinoma were positive for CK7, Napsin‐A (focal), and CDX‐2, negative for NKX3.1 and PSA." (PMID 40028792, 2025).
mucinous adenocarcinoma (continued). "Colloid carcinomas are generally positive for CK7 and CDX2 and weak or negative for TTF1, napsin A and EMA (MUC1)." (PMID 41473421, 2025). "Immunohistochemistry demonstrated the expression of cytokeratin 20 (CK20) and caudal-type homeobox transcription factor 2 (CDX2) with a lack of CK7, confirming pulmonary metastasis of colonic mucinous adenocarcinoma." (PMID 40166586, 2025). "Pathological examination of tissue from excisional biopsy of an inguinal lymph node revealed mucinous adenocarcinoma with immunohistochemistry (IHC) positive for cytokeratin (CK) 7, CK20 and GATA3, and negative for CK5/6, CDX2 and p63." (PMID 34997908, 2022).
colitis (21 papers, 2011 to 2025). Inflammation of the colon. "The link between CDX2 and matriptase is further interesting as they both affect intestinal inflammation and colitis-associated cancer." (PMID 30087389, 2018). "Moreover, the current study shows a novel link between VIP and Cdx2 activation; however further studies are required to better understand the relation between VIP, Cdx2, and susceptibility to colitis." (PMID 25932952, 2015). "To establish the role of DCLK1 and its isoforms in the progression of colitis, we mated DCLK1fl/fl mice with CDX2-Cre/ERT2 mice to develop DCLK1ΔIEC mice using tamoxifen-induced Cre recombination." (PMID 40839695, 2025). "Supplementation with SBP significantly restored the levels of ZO-1, occludin, Muc2, Muc3, and CDX2 in the colon of colitis mice, approaching near-normal levels." (PMID 38732527, 2024). "At the transcriptional level, the recovery of colitis-injured mucosa in vitro is impeded by upregulated Claudin-2 expression facilitated through a CDX2-dependent mechanism." (PMID 38619276, 2024). "Exosomal CagA promotes colitis by caudal type homeobox 2 (CDX2)-dependent claudin-2 upregulation in the intestinal epithelial cells." (PMID 39610678, 2024). "Specifically, CagA upregulated Claudin-2 expression at the transcriptional level via a CDX2-dependent mechanism to slow the restoration of wounded mucosa in colitis in vitro." (PMID 35331316, 2022). "Our previous study indicated that natural flavonoid baicalein ameliorated DSS-induced colitis via a caudal type homeobox 2 (Cdx2)-mediated PXR activation mechanism." (PMID 32372959, 2020). "In contrast, colitis that was induced by DSS treatment was comparable between Cdx2-Cre;Gankyrinf/f and control mice." (PMID 31941439, 2020). "In previous study, we have shown that flavonoid baicalein alleviates DSS colitis through the caudal type homeobox 2 (Cdx2)-mediated PXR activation mechanism." (PMID 31719637, 2019). "Nevertheless, heterozygous Cdx2+/- mice are reported to suffer increased intestinal permeability and heightened susceptibility to DDS-induced colitis suggesting a causal relationship." (PMID 25932952, 2015). "Our group have previously reported the potent anti-inflammatory activity of baicalein on dextran sodium sulfate (DSS)-induced colitis in mice, a well-established experimental model with features resembling human UC, via targeting to caudal-type homeobox 2 (CDX2/pregnane X receptor (PXR) pathway." (PMID 29180692, 2017). "Also, the expression of CDX2 and SATB2 has been shown to be decreased in the epithelium of patients with inflammatory bowel disease, and Satb2-deficient mice are more prone to the development of colitis and colitis-associated cancer compared with control mice." (PMID 39998677, 2025). "Thus, although the mechanism of MUC2 induction by IL-18 remains unknown, this stimulatory effect of IL-18 on MUC2 expression via CDX-2 upregulation seems to contribute to alleviation of colitis." (PMID 27966619, 2016). "Altered expression of CDX2 can disrupt the mucosa in protecting the host against its luminal components in the intestine, resulting in an increased expression of inflammatory mediators leading to colonic inflammation as observed in inflammatory bowel disease (IBD)." (PMID 25365201, 2014). "CDX2 expression is significantly decreased in patients with active UC, and it is involved in protection against DSS-induced colitis." (PMID 35331316, 2022). "Baicalin was proved to exert a remarkable anti-inflammatory effect on colitis induced by dextran sodium sulfate (DSS), and the mechanistic investigation revealed that it may be regulated through the caudal-type homeobox 2 (CDX2/pregnane X receptor (PXR) pathway." (PMID 32988394, 2020).
lung adenocarcinoma (21 papers, 2007 to 2026). A carcinoma that arises from the lung and is characterized by the presence of malignant glandular epithelial cells. "The combination of CK7 with CK20 and CDX2 is usually helpful to differentiate primary lung adenocarcinoma, classically positive for CK7, from metastatic colorectal carcinoma, which is usually negative for CK7 and positive for both CK20 and CDX2." (PMID 36835963, 2023). "Immunostaining of tumor cells were positive for thyroid transcription factor‐1 (TTF‐1) and cytokeratin 7 (CK7), while negative for caudal‐related homeobox transcription factor 2 (CDX‐2) and cytokeratin 20 (CK‐20), indicating a lung adenocarcinoma origin." (PMID 28781870, 2017). "Additionally, FOXA2 and CDX2 cooperate with NKX2-1 to inhibit metastasis in lung adenocarcinoma." (PMID 36289750, 2022). "CK20 and CDX2 positivity, combined with TTF‐1 negativity, strongly suggest intestinal differentiation in primary lung adenocarcinomas." (PMID 39980580, 2025). "The immunohistochemical markers of lung adenocarcinoma (CK7, TTF-1, Napsin A) and enteric differentiation (CDX-2, CK20, MUC2, villin) were both expressed in PEAC." (PMID 35172862, 2022). "In lung adenocarcinoma, the developmental transcription factors FOXA2 and Cdx2 function cooperatively with Nkx2-1 as an important regulator in inhibiting metastasis." (PMID 31007610, 2019). "CRC lung metastases commonly stain positive for CK20, CDX-2, and SATB2, whereas primary lung adenocarcinomas commonly stain positive for CK7, TIF-1, and napsin A." (PMID 30764882, 2019). "Immunostaining with TTF-1, CDX2, CK7 and CK20 has been found to be helpful in highlighting occurrences of primary lung adenocarcinoma." (PMID 21308162, 2010). "To our knowledge, CDKN2A EX2, CDX2, HOXA1 and OPCML constitute the strongest lung adenocarcinoma DNA methylation markers identified to date, and we are working on further evaluations of their potential with great anticipation." (PMID 17967182, 2007). "Based on the results of our analyses, four loci that are very strong candidates for a DNA methylation panel aimed at early lung adenocarcinoma detection have been identified: CDKN2A EX2, CDX2, HOXA1 and OPCML." (PMID 17967182, 2007). "The four most highly ranked loci, CDKN2A EX2, CDX2, HOXA1 and OPCML, which show significant DNA methylation even in stage IA tumor samples, merit further investigation as some of the most promising lung adenocarcinoma markers identified to date." (PMID 17967182, 2007). "Gastroscopic biopsy pathology showed: adenocarcinoma in the fundus near the cardia, immunohistochemistry CDX2(−), CK20(−), CK7(+), NapsinA(+), TTF-1(+), Villin(−), and lung adenocarcinoma metastasis was considered in combination with medical history and immunohistochemistry." (PMID 37695388, 2023). "Thus, we suggest that CDKN2A EX2, CDX2, HOXA1 and OPCML are the top candidates from the 28 tested, and should be validated as DNA methylation markers for lung adenocarcinoma." (PMID 17967182, 2007). "Lung CT-guided puncture biopsy, immunohistochemistry ALK (D5F3) (−), CD56 (−), CDX2 (−), CK20 (−), CK5/6 (−), CK7 (+), EGFR (+), Ki67 (hot zone + 40%), P40 (−), TTF-1 (+), Villin (−), combined with immunohistochemistry, led to the diagnosis of adenocarcinoma of the lung." (PMID 37695388, 2023). "Pathological examination of liver puncture biopsy with immunohistochemistry TTF-1(+), NapsinA(+), CK7(+), CDX-2(−), villin(−), CK20(−), HepPar-1(−), CK19(foci +), Ki-67(+, 40%), CD10(−), combined with medical history and immunohistochemistry, supported liver metastasis from lung adenocarcinoma." (PMID 37695388, 2023). "In comparison, SATB2 and CK20 showed higher specificity, with expression in 5% and 10% of mucinous primary lung adenocarcinomas and both in 0% of TTF-1-negative non-mucinous primary lung adenocarcinomas (25–50% and 5–16%, respectively, for GPA33/CDX2/CDH17)." (PMID 37349623, 2024).
lung adenocarcinoma (continued). "Using the current tissue collection and 5-fold cross validation, the four most significant loci (CDKN2A EX2, CDX2, HOXA1 and OPCML) individually distinguish lung adenocarcinoma from non-cancer lung with a sensitivity of 67–86% and specificity of 74–82%." (PMID 17967182, 2007). "Additionally, the lung mass was histologically similar to the resected urachal carcinoma, with positive expression of CK7, CK20, Villin, and CDX2, and negative for GATA3, TTF1, and NapsinA, supporting the diagnosis of metastatic urachal carcinoma rather than primary lung adenocarcinoma." (PMID 39462217, 2024).
colonic adenocarcinoma (20 papers, 2010 to 2025). "CK-20 and CDX-2 are markers commonly associated with colonic adenocarcinoma, while TTF-1 and CK-7 are markers of pulmonary epithelial cells and pulmonary adenocarcinoma, respectively." (PMID 31484545, 2019). "CDX2 protein was expressed uniformly in almost all primary colonic adenocarcinomas, including 82% mucinous variants which showed strong nuclear staining." (PMID 31689847, 2019). "However, reduced SATB2 expression (similar to that of CDX2) has been reported in mismatch repair deficient colon adenocarcinomas and small intestinal cancers." (PMID 32867793, 2020). "While comparing the usefulness of CDH17 in immunohistochemical diagnostics in gastrointestinal carcinomas with CDX2, it has been observed that almost all colon adenocarcinomas (99%) are CDH17-positive/CDX2-positive." (PMID 35055034, 2022). "In contrast, colon adenocarcinoma showed a significant enrichment of TFs such as CDX2 (26.5%), CDX1 (24%), HOXA13 (22%), HNF4G (37.2%), and TCF4 (36%) in gained peaks; and FOS::JUNB (45.4%), FOS::JUND (47.5%) and JUNB (46.3%) in lost peaks." (PMID 34090364, 2021). "It has been reported that CDX-2, a transcription factor involved in the proliferation and differentiation of intestinal epithelial cells, is an important biomarker for colon adenocarcinoma." (PMID 33087120, 2020). "The histologic report described mucoid material with necrosis and positive for pan-keratin and CDX2 stains, which was highly suspicious for colon adenocarcinoma." (PMID 31689847, 2019). "CK7, CK20, CDX2, thrombomodulin, and β-catenin can help distinguish primary bladder adenocarcinoma from colonic adenocarcinoma; PSA and PSAP can help distinguish primary bladder adenocarcinoma from prostate adenocarcinoma." (PMID 27006847, 2016). "The sensitivity and specificity of antibodies to CDX2 protein as a marker of colonic adenocarcinoma has been recently evaluated in various studies with reported sensitivity and specificity of greater than 90%." (PMID 22268990, 2012). "In comparison with the CK7-/CK20+ immunoprofile Tot found that CK7-/CK20+ expression pattern was more specific for colonic adenocarcinoma metastases than CDX2 alone (98.7% vs 90%), but less sensitive (79.5% vs. 84%)." (PMID 22268990, 2012). "These heterozygous-null Cdx2 mice are also sensitive to the azoxymethane (AOM)-induced colonic adenocarcinoma." (PMID 22719836, 2012). "All primary and 25 of 26 metastatic colonic adenocarcinomas showed high levels of CDX2 expression (2+ or 3+) in this study." (PMID 22268990, 2012). "Moreover, immunohistochemistry for cytokeratin 20 (CK-20) and caudal-type homeobox 2 (CDX2) can accurately identify colon adenocarcinoma origin." (PMID 36451153, 2022). "Recent studies, based on immunohistochemical and molecular findings, have shown that the expression in these tumors of CEA, CDX2, CK7 and CK20 is similar to that of colonic adenocarcinomas." (PMID 36278575, 2022). "Regarding immunohistochemistry, adenocarcinoma of the urinary bladder expresses CEA, CDX-2, MUC-1, MUC-2 and MUC-3, same as colonic adenocarcinoma." (PMID 20205820, 2010). "The expression of CDX2 is a sensitive and specific marker for the secondary type, arising from anorectal or colonic adenocarcinoma, but CDX2 fails to distinguish primary disease from EMPD secondary to urothelial or prostatic malignancy." (PMID 29943205, 2018). "Colonic adenocarcinoma typically expresses CDX2, but it is negative for CK7 and positive for CK20 and expresses β-catenin in a nuclear pattern." (PMID 27006847, 2016). "Colonic adenocarcinoma can stain with CK20, villin, monoclonal CEA, CDX-2, and Moc31." (PMID 24963429, 2014). "For example, in the study described here, 114 of 118 cases of colonic adenocarcinoma were CDX2-positive, independent of tumor grade." (PMID 22268990, 2012). "By contrast, colonic adenocarcinoma, while positive for CK20 and CDX2, is negative for CK7 and positive for thrombomodulin and nuclear β-catenin." (PMID 27006847, 2016).
colonic adenocarcinoma (continued). "Additionally, when tested on SW620 human colonic adenocarcinoma cells, CUR exposure enhanced the expression of a negative regulator (i.e., caudal-type homeobox-2 (CDX2)) in the CDX2/Wnt β-catenin signaling pathway." (PMID 34621313, 2021).
metastatic tumors (20 papers, 2012 to 2025). "We revealed expression of CK8/18, CK20, and CDX2 in both primary and metastatic tumors in our patient, which confirmed the etiology of skin metastasis." (PMID 39518386, 2024). "CDX2 immunoexpression has proven to be useful in establishing gastrointestinal origin in metastatic tumors." (PMID 34598716, 2021). "Moreover, metastatic tumors with CDX2 expression had higher CK20 expression in contrast to metastatic tumors with CDX2 knockdown, which suggests they were more differentiated." (PMID 33755595, 2021). "Additionally, IHC staining revealed that metastatic tumors with high CDX2 expression had higher E-cadherin expression in comparison to metastatic tumors with low CDX2 expression." (PMID 33755595, 2021). "Surprisingly, CDX2 knockdown inhibited the growth of metastatic tumors in the liver." (PMID 33755595, 2021). "Indeed, Ki-67 staining revealed metastatic tumors with CDX2 expression were more proliferative than metastatic tumors with CDX2 knockdown." (PMID 33755595, 2021). "In summary PTCT has a good prognosis with the 5-year overall survival rate of 78.7% and the 5-year specific survival rate of 84.3% and should be alternatively considered in Cdx-2 positive metastatic tumor of unknown origin." (PMID 33317491, 2020). "Our real-world data shows that mCRC patients who have non-resectable metastatic disease with CDX2 loss have a worse prognosis, receive less first- and second-line chemotherapy with less benefit and rarely receive secondary surgery." (PMID 32117703, 2020). "Primary testicular carcinoid tumor with Cdx-2 positive stain outlines an exceptionally rare neoplastic entity without a consensus about general follow-up guidelines, requiring close clinical and imaging aftercare and consideration in Cdx-2 positive metastatic tumor of unknown origin." (PMID 33317491, 2020). "Firstly, we performed the TF enrichment analysis between primary tumors and metastatic tumors, and finally, seven TFs were identified as differentially expressed TFs, including CBX2, CDX2, FOXA2, KLF4, NANOG, NCAPG, and TFAP2A, which was demonstrated in a heatmap and a volcano plot." (PMID 38702698, 2024). "At diagnosis, patients with metastatic disease were 10 (83.3%) in the CDX-2 positive subgroup and one (50%) in the CDX-2 negative subgroup." (PMID 36928082, 2023). "All cases histologically resembled well-differentiated NETs of visceral origin with Ki-67 proliferation indices of 5–42% and expression of T-PIT; metastatic tumors were not immunoreactive with CDX2, Islet 1 or TTF-1." (PMID 32622369, 2020). "GATA3, TTF-1, S100, p40, PAX8, p63, NKX3.1, CDX2, SALL4, CD30 (-) were detected to rule out metastatic disease." (PMID 40978995, 2025).